ALPP (alkaline phosphatase, placental)
Diseases named in the same sentence as ALPP in open-access papers (continued):
Sharing a sentence is not in itself a finding about the gene and the disease.
tumor (29 papers, 1984 to 2025). "Clinical risk factor analysis identified CA19-9, a critical tumor marker for digestive cancers, as significantly elevated in patients with high ALPP expression." (PMID 41209549, 2025). "High ALPP expression was found to be associated with increased serum levels of the tumor marker CA19-9, enhanced infiltration of immune cells, including B cells and dendritic cells, and potential activation of the PI3K-Akt signaling pathway." (PMID 41209549, 2025). "ALPPL2 belongs to the member of the ALPP alkaline phosphatases which are reported to be associated with tumor initiation." (PMID 34441816, 2021). "Targeting ALPP could hypothetically reduce immune evasion and render the tumor more susceptible to immunotherapy." (PMID 41209549, 2025). "An increase in plasmacytoid dendritic cells, which are associated with poorer survival in solid tumors 35, in ALPP-high CCA tumors could impair effective anti-tumor immunity." (PMID 41209549, 2025). "However, the molecular mechanisms underlying involvement of ALPP in tumor progression, as well as its prognostic significance, particularly in CCA, remain largely undefined." (PMID 41209549, 2025). "Existing research provides insufficient evidence regarding the involvement of ALPP in CCA tumor development, metastasis, and its interaction with the tumor immune microenvironment, highlighting a significant gap in current knowledge." (PMID 41209549, 2025). "The methylation status of individual CpG sites was further compared between tumor and normal tissues, as well as in relation to ALPP expression." (PMID 41209549, 2025). "We further assessed the relationship between ALPP expression and tumor-infiltrating immune cells, focusing on B cells and dendritic cells (DCs)." (PMID 41209549, 2025). "These possibilities suggest that ALPP contributes to immune evasion by qualitatively altering the tumor-infiltrating immune cells." (PMID 41209549, 2025). "Our findings suggest that CCA may exploit distinct methylation sites within the ALPP gene to influence tumor progression, highlighting the potential of ALPP methylation as a novel epigenetic marker in CCA." (PMID 41209549, 2025). "We selected ALPP expression levels that were positively correlated with tumor purity." (PMID 41209549, 2025). "Likewise, in vitro and in vivo functional assays (e.g., ALPP knockdown in CCA cell lines or xenograft models) will be important to determine whether ALPP actively drives tumor progression or immune modulation." (PMID 41209549, 2025). "Therefore, ALPP might indirectly promote tumor progression by attenuating anti-tumor immunity." (PMID 41209549, 2025). "We further explored the relationship between ALPP expression and tumor-infiltrating immune cells within the CCA tumor microenvironment (TME." (PMID 41209549, 2025). "The expression of RSPO3, ALPP, VEGFC, ANXA8, HES2, GLP2R, and KRT14 in normal tissues was significantly higher than that in tumor tissues." (PMID 38240936, 2024). "MUC16 showed significant co-expression with antigens (tumor-antigens & autoantigens) and acute phase reactants such as transglutaminases (TGM2), CEACAMs, C-Reactive Protein (CRP), and alkaline phosphatase (ALPP)." (PMID 36816942, 2023). "ALPP expression was higher in primary site tumor samples when compared to normal and metastatic samples while TSPAN15 was upregulated in primary site tumor and metastatic samples as compared to normal samples." (PMID 37047289, 2023). "Taken together, these findings suggest that ALPP may contribute to CCA progression by regulating extracellular matrix remodeling and activation of PI3K-Akt signaling, thus offering new insights into its functional role in tumor biology." (PMID 41209549, 2025). "Furthermore, ALPP may regulate critical signaling pathways in CCA, including the activation of the PI3K-Akt signaling pathway, thereby potentially contributing to tumor progression." (PMID 41209549, 2025).
cancer (15 papers, 2013 to 2025). A tumor composed of atypical neoplastic, often pleomorphic cells that invade other tissues. "The gene coding for PLALP is defined as ALPP, and the gene can be re-expressed by cancer cells as the Regan isoenzyme." (PMID 34943845, 2021). "In light of this, ALPP is not only a biomarker but also a potential therapeutic target; indeed, placental alkaline phosphatase is being explored as a target for immunotherapy in other cancers." (PMID 41209549, 2025).
infection (2 papers, 2005 to 2020). The state of being infected such as from the introduction of a foreign agent such as serum, vaccine, antigenic substance or organism. "Furthermore, we analyzed the production of ZIKV SZ01 and MR766 virions from infected wild-type (WT) and ALPP−/− JEG-3 cells over an infection period of 72 h and found that ALPP depletion markedly reduced the release of ZIKV virions." (PMID 32934082, 2020).
ALPP also shares sentences with these, for which no sentence is quoted: germinoma (10 papers); seminoma (8); dysgerminoma (6); embryonal carcinoma (3); yolk sac tumor (3); choriocarcinoma (2); esophageal squamous cell carcinoma (2); renal cell carcinoma (2); cardiovascular disease (1); cervical carcinoma (1); childhood asthma (1); cryptorchidism (1); endometrial adenocarcinoma (1); gastric cancer (1); GI tumor (1); gonadoblastoma (1); hypophosphatasia (1); incontinence (1); leukemia (1); Leydig cell tumor (1); lung carcinoma (1); melanoma (1); microcephaly (1); Obesity (1); ovarian clear cell cancer (1); ovarian tumors (1); pancreatic adenocarcinoma (1); Parkinson disease (1); perinatal disease (1); prostate carcinoma (1).
A further 6 diseases each share a sentence with ALPP in 1 paper.